CBS (cystathionine beta-synthase)
Diseases named in the same sentence as CBS in open-access papers (continued):
Sharing a sentence is not in itself a finding about the gene and the disease.
Down syndrome (continued). "CBS gene is located on human chromosome 21, the chromosome that has an extra copy in trisomy 21 called Down syndrome." (PMID 32365821, 2020). "Recent studies on Down syndrome fibroblasts, using pharmacological inhibition of CBS, as well as genetic silencing of CBS, indicated that the metabolic inhibition seen in Down syndrome cells, is at least, in part, caused by the overproduction of H2S by CBS." (PMID 32340322, 2020). "The potential role of the CBS/H2S pathway in Down syndrome, and potential experimental and clinical approaches focusing on CBS inhibition and/or H2S scavenging have recently been reviewed." (PMID 32365821, 2020). "Which enzyme, then, is more important in the suppression of mitochondrial function in Down syndrome, CBS or 3-MST?" (PMID 32340322, 2020). "CBS is localized to astrocytes adjacent to the senile plaques in the brains of Down’s syndrome patients." (PMID 32477150, 2020). "CBS is up-regulated in several diseases, including Down syndrome and many forms of cancer; in these conditions, the preclinical data indicate that inhibition or inactivation of CBS exerts beneficial effects." (PMID 32365821, 2020). "In other conditions (best characterized in Down syndrome), elevated CBS levels yield toxic concentrations of H2S, which are deleterious to the cell." (PMID 32365821, 2020). "(There are, in fact, several prior examples of endogenously produced H2S suppressing, rather than increasing mitochondrial function: for instance, CSE-derived H2S does so in normal mouse liver and CBS-derived H2S does so in Down Syndrome fibroblasts)." (PMID 32183148, 2020). "Instead, we have primarily focused on the mechanisms and consequences of CBS up-regulation, in particular in the context of Down syndrome and cancer." (PMID 32365821, 2020). "Ten years later, the up-regulation of CBS enzyme (an expected “gene dosage” effect) and a consequent increase in CBS enzymatic activity was demonstrated in fibroblasts from Down syndrome individuals." (PMID 32365821, 2020). "As expected, CBS up-regulation in Down syndrome resulted in low plasma and tissue homocysteine levels." (PMID 32365821, 2020). "CBS expression is threefold higher in patients with Down's syndrome than in normal controls, whereas CBS expression is lower in children with high IQ scores." (PMID 29507650, 2018). "For example, the increased dosage of CBS and GCS in our simulation of Down syndrome causes the intracellular concentration of cysteine to decline while the blood concentration increases." (PMID 18442411, 2008). "To investigate the metabolite profile of Down syndrome using the model, we began by increasing by 50% the Vmax of CBS, since the gene for CBS is on chromosome 21 and is expressed at 150% of normal." (PMID 18442411, 2008). "People with Down syndrome have an extra copy of the CBS gene, leading to overproduction of H2S." (PMID 40998690, 2025). "Interestingly, a similar, perhaps also compensatory upregulation of H2S degrading enzymes is also noticeable in Down syndrome models, where CBS and 3-MST are upregulated, but this is also accompanied by an upregulation of various H2S catabolizing enzymes." (PMID 39643979, 2024). "The sensitivity of cytosine arabinoside in Down Syndrome myeloblasts is influenced by CBS activity." (PMID 39062461, 2024). "Overexpression of CBS was observed in the hippocampus and cortex of Down syndrome mice." (PMID 39148948, 2024). "The opposite may be true of diseases involving elevated H2S, such as Down syndrome, in which the trisomy of chromosome 21 leads to excess H2S production due to an extra copy of CBS." (PMID 37237961, 2023). "At the same time, the science has progressed to the point where Down syndrome and several forms of cancer can be considered to be “validated targets” for intensified translational efforts for the discovery and development of pharmacological CBS inhibitors." (PMID 32365821, 2020).
Down syndrome (continued). "In the early 2000s, Kamoun observed an elevation of H2S metabolites in the circulation and urine of Down syndrome individuals and hypothesized that overproduction of H2S by CBS may induce some of the clinical signs of DS." (PMID 32365821, 2020). "Indeed, the upregulation of CBS has been well documented in various cells and tissues of animals or human subjects with Down syndrome." (PMID 32340322, 2020). "CBS—localized on chromosome 21—is overexpressed in Down syndrome cells and tissues [reviewed in 5]." (PMID 32340322, 2020). "Therefore, it has been suggested that CBS inhibitor-containing treatment might be preferable for improving the quality of life in individuals with Down syndrome." (PMID 39148948, 2024). "Moreover, at least in the case of CBS-derived H2S, the effect of CBS inhibition or CBS silencing can be reversed by GYY4137 in Down syndrome cells, pointing to a direct involvement of H2S in the bioenergetic dysfunction associated with Down syndrome." (PMID 32340322, 2020). "The results of the current study, however, indicate that in addition to CBS, a second H2S-producing enzyme, 3-MST, may also contribute to the cellular bioenergetic disturbances in Down syndrome fibroblasts." (PMID 32340322, 2020). "The findings presented in the current report suggest that in addition to the indisputable role of CBS, H2S produced from 3-MST may also contribute to the development of mitochondrial metabolic and functional impairments in Down syndrome cells." (PMID 32340322, 2020). "(It should be, nevertheless, noted that the genes located on chromosome 21 are located on 3 different mouse chromosomes, and many of the mouse models of Down syndrome, unfortunately, do not include murine CBS, and therefore are only of limited translational relevance for the human disease)." (PMID 32365821, 2020).
Hypertension (22 papers, 2013 to 2025). The presence of chronic increased pressure in the systemic arterial system. "For instance, low levels of the CBS gene due to epigenetic imbalance (i.e., CBS hypermethylation) enhanced the risk of hypertension in humans." (PMID 37509058, 2023). "For example, deficiency in CBS or another H2S-synthesis enzyme cystathionine γ-lyase (CSE or CTH) causes hypertension in mice." (PMID 32006269, 2020). "Studies using various animal models of HHcy, including CBS knockout mice and Hcy-supplemented rats, have shown that HHcy induces collagen deposition, increased wall thickness, and arterial stiffness, predisposing the vasculature to hypertension and remodeling." (PMID 39898976, 2025). "Endogenous hydrogen sulfide (H2S) and its key generating enzyme, cystathionine β-synthase (CBS), prevent vascular remodeling and damage to target organs during the advancement of hypertension induced by a high-salt diet." (PMID 40642013, 2025). "Of these genes, A2ML1, AGGF1, CBS, ECE1, GABRB3, GALNT2, MRPS6/SLC5A3, and SPG7 had documented associations with hypertension, ischemic stroke and methionine metabolism, atherosclerosis, and early-onset MI." (PMID 34252155, 2021). "This study also found a complete reversal of the hypertension and collagen deposition, as well as a decrease in the CBS+/− wall to lumen ratio." (PMID 29595876, 2018). "Previous studies showed that H2S/CBS pathway of renal tissue was downregulated in the formation of hypertension." (PMID 26823949, 2016). "Moreover, in models of cardiac arrest and lateral percussion-induced TBI, NaHS stabilizes the BBB by inhibiting MMP-9 and occludin, prevents vascular dysfunction, hypertension, and sympathetic hyperactivity, and restores CBS, CSE, and eNOS expression." (PMID 41465271, 2025). "Deficiency in CBS or CSE causes marked hyperhomocysteinemia and hypertension in mice." (PMID 32006269, 2020). "Endogenous activation of CBS, showing an increasing H2S, could be a therapeutic approach to prevent deleterious vascular remodeling and hypertension." (PMID 31572179, 2019). "The fact that DEX reduces the CBS and CSE expression has also been observed in animal models such as DEX-induced hypertension and osteoporosis in the rat or LPS-induced endotoxic shock." (PMID 35682634, 2022). "Both proteins, CBS and CTH, were showed in arterial wall of lobar arteries of both normotensive patients and patients with arterial hypertension." (PMID 32585916, 2020). "Our study demonstrates that Hcy metabolism enzymes, CBS and CSE are greatly diminished in Ang II-induced hypertension." (PMID 24386282, 2013). "It is interesting to note that the difference in CBS expression did not occur until hypertension developed." (PMID 26078823, 2015). "Similarly, the occurrence of arterial hypertension did not affect the transcription of the CBS gene in the lobar arterial wall (AH: 2.48 ± 0.49; n = 7 vs. NT: 2.93 ± 0.43; n = 6)." (PMID 32585916, 2020).
diabetes (17 papers, 2008 to 2026). "We also found an increased glucagon expression, a hallmark of diabetes, which led to worsening of the hyperglycemia in the islet of mice deficient in CBS." (PMID 35681432, 2022). "The results revealed that diabetes reduced the expressions of CSE and CBS protein (P < 0.05), while the inductor of HO-1 restored diabetes-induced loss of CSE and CBS protein expression (P < 0.05)." (PMID 26798657, 2016). "To determine whether changes in CBS levels are associated with altered Hcy levels in diabetes, we tested the CBS level in the serum of diabetic patients and experimental diabetic animals." (PMID 30669482, 2019). "Alteration of H2S levels is now considered a key event in the pathogenesis of diabetes and associated complications as for instance, a downregulation in CSE and CBS expression favours progression of diabetic cardiomyopathy." (PMID 37335394, 2023). "We also found DNA demethylation of cystathionine-β-synthetase (CBS), which is the endogenous H2S-producing enzyme, induced gastric hypersensitivity in rats with diabetes." (PMID 31781662, 2019). "Second, it was consistently shown that in rats with diabetes, the expression of CBS is significantly increased." (PMID 28331553, 2017). "Furthermore, mitochondrial CBS activity was markedly reduced in DM rats, reinforcing the impairment of mitochondrial H2S production in diabetes." (PMID 40867642, 2025). "Elevated serum or plasma levels of homocysteine are theorized to be secondary to impairments in metabolism, including cystathionine-synthase (CBS) deficiency or methylenetetrahydrofolate reductase (MTHFR) deficiency, certain disease states such as diabetes, or dietary deficiencies." (PMID 39583366, 2024). "For this purpose, we compared the expression of CSE and CBS in synovium from OA and OA-DB patients and evaluated the effect of a slow-releasing donor of H2S on macrophage polarization in TPH-1 cells differentiated into macrophage under an in vitro model of diabetes-associated glucotoxicity." (PMID 37335394, 2023). "In vivo, in streptozotocin-induced diabetes, a T2DM model, the levels of CBS and CSE increase in both the pancreas and liver as well as in islet β cells of diabetic animals." (PMID 32993056, 2020). "Animal models of diabetes exhibited reduced serum H2S concentrations without changes in the tissue expression of the H2S synthesizing enzymes, cystathionine-β-synthase (CBS), and cystathionine-γ-lyase (CSE)." (PMID 35351094, 2022). "Reduced expressions of CBS and CSE have been found in diabetes." (PMID 26798657, 2016).
glioma (17 papers, 2017 to 2025). A benign or malignant brain and spinal cord tumor that arises from glial cells (astrocytes, oligodendrocytes, ependymal cells). "Activation of CBS promoted tumor growth in colon, ovarian, breast, prostate, and lung cancers, whereas loss of CBS in glioma cells increased tumor volume in vivo." (PMID 35758651, 2022). "It has been proven that higher expression of CBS is associated with better prognoses in IDH-mutated 1p/19q-codeleted gliomas." (PMID 35053475, 2022). "Enhanced glioma tumorigenicity upon CBS loss was associated with upregulation of HIF-2α protein level and HIF-2α-dependent transcriptional activation of angiopoietin like 4 (ANGPTL4) and vascular endothelial growth factor A (VEGFA)." (PMID 30050925, 2018). "The underlying mechanism remains unclarified, and reduced expression of CBS in glioma tumor cells may cause upregulation of 3-MST to generate H2S production alternatively." (PMID 34207284, 2021). "In contrast, it was reported that CBS is involved in suppressing glioma, whereby glioma with suppressed CBS had high levels of VEGF and HIF-2α and was deeply invaded with dense vascularization and aggressive growth." (PMID 34208749, 2021). "Higher HSPB1 was found to contribute to glioma development, while CBS expression, consistent with our results, was reduced in glioma progression." (PMID 34819946, 2021). "Decreased expression of CBS promotes the formation of glioma tumors by increasing the HIF-2α protein levels and HIF-2 target gene expression." (PMID 32733879, 2020). "Since Takano and coworkers have found that reduced CBS expression promotes glioma tumorigenesis, our results are in line with their observation, since tumorigenicity increased with a grade." (PMID 29793450, 2018). "Based on the expression of almost 600 patients, we found that the levels of CBS and GCLc were significantly upregulated in IDHm compared to IDHwt gliomas supporting a higher activation of the transsulfuration pathway." (PMID 29054837, 2017). "We found that genes coding for key enzymes in de novo glutathione synthesis are highly expressed in IDH‐mutant gliomas and the expression of cystathionine‐β‐synthase (CBS) correlates with patient survival in the oligodendroglial subtype." (PMID 29054837, 2017). "In addition, higher expression of OGT, FOXC1, ASNS, GPT2, CBS, or FTH1 was also associated with poorer outcomes in clinical cases with renal clear cell carcinoma or glioma." (PMID 40416363, 2025). "CBS deficiency in U87-MG glioma cells did not affect cell proliferation in 2D culture but increased colony formation in soft agar, indicative of enhanced anchorage-independent growth." (PMID 30050925, 2018). "Evidence from glioma supports a tumor-suppressive role for CBS." (PMID 30050925, 2018). "The increased expression of CBS and GCLc in IDHm gliomas supports the idea that IDHm tumors may preferentially utilize the transsulfuration pathway for GSH synthesis." (PMID 29054837, 2017). "Interestingly, when investigating the relationship between CBS and patient prognostic, a high CBS expression was associated with a better patient survival in IDHm‐1p/19q co‐deleted gliomas, suggesting that CBS can be used as a novel prognostic biomarker in this specific subgroup of gliomas." (PMID 29054837, 2017). "The differential expression of CBS, CDO1, and TfR1 underscores a metabolic vulnerability in high-grade gliomas." (PMID 41154707, 2025). "Among IDHm gliomas, CBS expression was higher in IDHm‐1p/19q co‐deleted gliomas compared to IDHm without 1p/19q co‐deletion, contrary to GCLc." (PMID 29054837, 2017). "Here, we identify CBS not only as a novel prognostic marker for 1p/19q co‐deleted IDHm gliomas (ODG subtype), but also as a potential target to tilt the balance toward high‐oxidative stress in IDHm gliomas." (PMID 29054837, 2017).
lung carcinoma (15 papers, 2013 to 2025). "As a newly identified CBS and NFκB repressor, we suggest that rpL3 could be used in association with 5-FU to enhance the susceptibility of lung cancer cells to this drug." (PMID 27924828, 2016). "Given the downregulation of CBS, GCLC, and GCLM in DDX3X-deficient lung cancer cells, we then questioned which enzyme primarily mediates the effects of DDX3X inhibition." (PMID 40885716, 2025). "CBS (Cystathionine-Beta-Synthase), which is involved in tumour metabolism and redox balance, was downregulated, aligning with its subtype-specific roles in lung cancer." (PMID 40559957, 2025). "LINC00336 was reported to inhibit ferroptosis in lung cancer cells by acting as a sponge for miR-6852 and positively regulating its target, CBS (cystathionine β-synthase)." (PMID 38534739, 2024). "In lung cancer tissues, the expression of rpL3 was down‐regulated and the expression of CBS was up‐regulated." (PMID 36929586, 2023). "In the lung cancer cell line Calu‐6 after 5‐FU treatment, rpL3 decreased its stability at transcriptional and post‐translational levels by targeting CBS to enhance the effect of 5‐FU on cancer cells' lethality." (PMID 36929586, 2023). "LINC00336 functions as an oncogene in lung cancer and regulates cystathionine-β-synthase (CBS) expression by competing for miR6852." (PMID 35223846, 2022). "CBS mRNA and protein levels are slightly up-regulated in chemically hypoxic A549 lung cancer cells treated with cobalt chloride." (PMID 36558139, 2022). "Increased levels of CBS protein or mRNA have also been reported in two different collections of lung cancer clinical specimens." (PMID 36558139, 2022). "For instance, in lung cancer cells, CBS was found to be down-regulated by the up-regulation of ribosomal protein L3 when treated with the common chemotherapy drug 5-fluorouracil; this was associated with the inhibition of cell migration and invasion." (PMID 32365821, 2020). "MicroRNA 6852 (MIR6852) was also found to regulate the expression of CBS and regulate lung cancer cell ferroptosis." (PMID 32365821, 2020). "Having established the expression profile of CBS and rpL3 in tumors we became interested to investigate the possible involvement of rpL3 in the control of CBS expression in lung cancer treatment." (PMID 27924828, 2016). "To evaluate CBS and rpL3 clinical significance in lung cancer, we employed quantitative real-time PCR (qRT-PCR) and immunoblotting to assess the expression of CBS and rpL3 at the mRNA and protein levels in 21 lung cancers and normal tissues." (PMID 27924828, 2016). "Comparison of human lung cancer specimens with patient-matched normal tissues revealed the up-regulation of CBS and the down-regulation of rpL3 in the cancers." (PMID 27924828, 2016). "Furthermore, we demonstrated that METTL16-dependent m6A modification is essential for DDX3X-regulated CBS expression and lung cancer proliferation." (PMID 40885716, 2025). "Our data indicated that patients with higher expression of DDX3X/CBS, DDX3X/METTL16 and DDX3X/JUND exhibited poorer overall survival and progression-free interval, suggesting the prognostic value of DDX3X and its associated genes for lung cancer patients." (PMID 40885716, 2025). "Notably, in lung cancer tissues, endogenous H2S and its producing enzymes, like cystathionine beta-synthase (CBS), cystathionine gamma lyase (CSE, also known as CTH) and 3-mercaptopyruvate sulfurtransferase (3-MST), are highly expressed thereby benefiting cancer development." (PMID 32195181, 2020). "Since existing knowledge underscores the predominant role of GCLC over GCLM in modulating cancer progression, we thereby individually silenced CBS and GCLC in lung cancer cells." (PMID 40885716, 2025).